TLR4 (toll like receptor 4)
Diseases named in the same sentence as TLR4 in open-access papers (continued):
Sharing a sentence is not in itself a finding about the gene and the disease.
infection (continued). "Our results indicated that unlike LPS stimulation per se that activates IRAK-1, infection with Leishmania rendered IRAK-1 activation refractory to this TLR4 agonist." (PMID 19104650, 2008). "TLR4-/- mice showed no significant change in infection course or pathology but some increases in cytokine production were observed compared to wt control mice and primary cell lines derived from these." (PMID 16995947, 2006). "LTA -+252 and CCC, TNFA-308 and CCC, IL10-819 rs1800871 and CCC, TLR4 haplotype D229G/T399I with protection from CCC, TIRAP S180L (rs8177374) and rs8177376 (strong linkage disequilibrium) with CCC, IL18 rs360719 and infection, IL17A rs4711998 and infection, TGFB1+10 rs1800470 with infection." (PMID 40297326, 2025). "However, when examining bacterial colonization at 4h post-infection, we found slightly higher bacterial loads in both brain tissue and blood of TLR4-/- mice compared to WT mice, though the difference was not statistically significant." (PMID 40821830, 2025). "Furthermore, as observed upon treatment with purified VCC, V. cholerae-induced cytokine production was also attenuated upon infection in the neutrophils, isolated from the TLR1-/-, MyD88-/- and C3H/HeJ (TLR4-defective), mice as compared to those from the wild type mice." (PMID 40184418, 2025). "Notably, we introduced paquinimod alongside antimicrobial therapy such that blocked TLR4 recognition of DAMPs occurred during and after pharmacological eradication of the bacteria—not during infection." (PMID 41073563, 2025). "In this study, we did not detect any changes in TLR4 mRNA production in response to infection with the HIV-1 sub-subtype A6 and subtype B (either with or without the presence of hormones), although several studies have shown that HIV infection can increase TLR4 expression in vivo and in vitro." (PMID 41305532, 2025). "Powdered infant formula supplemented with HMOs protects the colon from infection and reduces the inflammatory response by preventing necrotizing small intestinal colitis (NEC) in mice or piglets and by inhibiting activation of the TLR4 signaling NF-κb signaling pathway." (PMID 38426086, 2024). "Clearance of macrophages or deletion of TLR4 (Toll‐like receptor 4, recognition of LPS) rather than Dectin‐1 (recognition of beta‐1,3/1,6 glucans on fungi) blocked the antifungal drug‐induced aggravation of lung inflammation during infection." (PMID 39429884, 2024). "In this study, at the 5th week after infection, the parasite load of undernutrition 65% + infection group in the spleen was the lowest, the expression of PD-1, PD-L1 and Bax in the spleen of this group was downregulated, and TCR, Bcl-2 and TLR4 were upregulated." (PMID 38185681, 2024). "Unlike the invasion mechanisms of protozoans, during infection by the nematode A. cantonensis, an increase in Cav-1 expression in the brain and through the TLR4/MyD88 signaling pathway to activate MMP-9 leads to degradation of tight junction proteins (Zo-1 and claudin-5)." (PMID 38922036, 2024). "Thus, high activation of innate immunity receptors (TLR4, TLR6) and inflammatory cytokines (such as pro-IL-1β) in Swiss mice during the acute phase of infection may contribute to the low parasite burden." (PMID 38896633, 2024). "Previous studies have suggested engaging TLR4 enhances Pa bacterial clearance, thus the use of INI-2002 may have additional benefits beyond increased antigen-specific antibody titers in a Pa infection setting." (PMID 38400099, 2024). "This raises the hypothesis that PAI-1 KO mice may have defective TLR4 signaling which is sufficient to protect them from LPS-induced inflammation, but not a polymicrobial infection." (PMID 38304613, 2023). "Similarly to our results, TL2 and TLR4 mRNA expression in the ileum was upregulated in CV pigs 24 h after infection with S. Typhimurium, but TLR9 mRNA expression was not influenced." (PMID 38003758, 2023).
infection (continued). "In addition, the activation of TLR2 and TLR4 in CD34+ cells and megakaryocytes in the presence of TPO may warrant platelet provision during infection episodes by an autocrine IL-6 loop triggered by the PI3K/NF-κB axes." (PMID 36674552, 2023). "These capillary responses to infection appear to be largely driven by TLR4 signaling, as determined by the response to LPS administration and by the blunting of these responses to bacterial infection in the absence of TLR4." (PMID 37318981, 2023). "Moreover, curcumin has been shown to the inhibit activation of pattern recognition receptors, such as Toll-like receptor 4 (TLR4), which play important roles in regulating the inflammatory response in the presence of infection via activation of cellular signaling pathways such as NF-κB." (PMID 37049389, 2023). "Rather, the downregulation of TLR4 and TLR6 in response to T15 and S10 infection, respectively, as well as the downregulation of expression of the adapter protein MYD88 during 8067 and T15 infection, was seen (albeit at low-fold changes, especially during T15 infection)." (PMID 38276150, 2023). "TLR4 uniquely signals through both the MyD88- and TRIF-dependent signaling cascades, but the respective contributions of these pathways in triggering trained immunity and host resistance to infection is unknown." (PMID 36439136, 2022). "hydrophila (a Gram-negative fish pathogen) infection could significantly up-regulate the expression of TLR4 from rohu (Labeo rohita)." (PMID 36292749, 2022). "Again, in line with our hypothesis of exaggerated responses to lung infection, many of the top upstream regulators identified by IPA were associated with enhanced inflammation (TNF, IFNG, and IL1B) and infection with Gram-negative bacteria (TLR4)." (PMID 36264633, 2022). "Furthermore, we found the TLR4/CD14/MD2 complex to be decisive for the uptake of Ct-derived lipopolysaccharides but not for infection and replication of Ct." (PMID 36557742, 2022). "TLR4 and CAP1 are expressed on human alveolar macrophages and type 2 alveolar cells, indicating that resistin could play a role in the lung immune response during infection." (PMID 35273609, 2022). "TLR4 may play an important role in the pathogenesis of SARS-CoV-2, its overactivation may lead to persistent or excessive innate immune response, and innate immune response is the key to identify and control infection by releasing cytokines and chemokines." (PMID 35935817, 2022). "We demonstrate that productive infection of macrophages can be altered by TLR signaling in response to purified ligands and bacterial coinfection, with TLR2- and TLR5-mediated signaling activating HIV-1 and TLR3- and TLR4-mediated signaling repressing HIV-1 replication in MDMs." (PMID 33472928, 2021). "At early time points of infection (2 and 8 h), VitD3 did not affect TLR4 expression." (PMID 34634046, 2021). "The process of type I IFN production by macrophages downstream of bacterial stimulation is well-established, especially for infections with Gram-negative bacteria wherein recognition of LPS by endosomal TLR4 leads to the activation of interferon regulatory factor 3 (IRF3)." (PMID 33684179, 2021). "Although LPS is widely known to be the PAMP recognized by TLR4 following infection by a range of Gram-negative pathogens, prior experimental assessments of L. pneumophila on this particular topic were murine-based and they had concluded that TLR2 is the receptor responding to L. pneumophila LPS." (PMID 34280250, 2021). "Hence, we thus focused on intestinal immune-related enzymes, intestinal antioxidant capacities, and physical barrier functions, regulated via the TLR4/MyD88/NF-kB and MLCK signaling pathway by using Songpu mirror carp with AKG supplementation after infection with A. hydrophila." (PMID 34220849, 2021). "TLR4 expression is not induced in either animal model at early infection." (PMID 35046936, 2021).
infection (continued). "Interestingly, although we observed the expected stimulation of TLR4 (Toll-like receptor 4) in the ground-based infection, this did not occur in the flight cultures at the time point evaluated." (PMID 33750813, 2021). "All turkeys that received vaccination and infection showed consequences on upregulation of TLR1B, TLR2B, TLR4, TLR6 and TLR7, whereas in chickens of the equivalent group, TLR1B, TLR2B and TLR21 were found to be increased in contrast to TLR4 and TLR7 which were decreased." (PMID 34579197, 2021). "Indeed, TLR2 and TLR4 were not necessary to reduce the growth of the pathogen following peripheral infection and to elicit the inflammatory response in the lungs following pulmonary infection." (PMID 34796128, 2021). "Thus, the results above from in-depth mechanistic experiments demonstrated that MIR337-3p targeted/depressed upstream TLR4/MYD88 and STAT3 signaling and the downstream VDR antimicrobial pathways of CYP27B1/DEFB4A/CAMP, leading to an enhanced mycobacterial entry/infection and growth." (PMID 34912331, 2021). "Thus, TLR4, IL27, and TNF were activated across all groups; IFNG was exclusively activated by AMTB-127 and AMTB-205; PTGS2 was activated in AMCTs and AMTBs in response to infection with Mtb UT205, whereas TLR2 was only activated in response to Mtb UT127." (PMID 32373118, 2020). "Similarly, there was limited immune response in LPS-treated macrophages blocked with TLR-4 antagonist which confirms that Gram-negative bacteria rely primarily on TLR4 during infection." (PMID 33212859, 2020). "TLR4 wild type (TLR4wild) and TLR4 defective (TLR4def) mice were orally infected with 45 metacercariae of C. sinensis, and all C. sinensis-infected mice and non-infected groups were anesthetized on day 28 post-infection." (PMID 33469517, 2020). "In agreement with the known principle for “TLR4 agonist” acylation pattern of lipid A, C. rodentium induces rapid TLR4-dependent responses in intestinal epithelium, although TLR4- mediated pro-inflammatory signaling is not host-protective and contributes to pathology and morbidity during infection." (PMID 33329561, 2020). "HIV-1BaL, a laboratory adapted CCR5-tropic HIV, infection rendered KCs more sensitive to LPS treatment through an increase in CD14 and TLR4 expression on the cell surface, resulting in increased secretion of TNF-α and IL-6, which was blocked by a small molecule TLR4 inhibitor." (PMID 32612603, 2020). "Although not examined in this study, previous investigations have demonstrated the abundance of TLR4 in human pulpal fibroblasts and LPS infection increased PGE2 and COX-2 expression, indicating the participation of TLR4 in pulpal innate immune response during an infection with cariogenic microbes." (PMID 32223750, 2020). "Since infection is not usually present in healthy term labour, endogenous DAMPs including HMGB1, cell‐free DNA and oxysterols released from senescent cells in fetal membranes and placenta are implicated in TLR4 signalling in term labour." (PMID 32313651, 2020). "We also investigated the interplay between nicotine, TLR2 and TLR4 for their reported role in infection by gram-negative and -positive bacterial infection, and subsequent effect on MyD88 signaling, inflammatory response, and bacterial load in infected macrophages." (PMID 33212859, 2020). "To examine infection-induced antibodies in this context, we transferred immune and non-immune serum into mice stimulated with TLR4 or TLR9 agonists, since Plasmodium infection can stimulate the innate immune system and pro-inflammatory cytokine production via these receptors." (PMID 30811498, 2019). "AVR-25 has a binding potency similar to the binding of chitohexaose with TLR4; hence, we hypothesized that, compound AVR-25 will have similar therapeutic efficacy as chitohexaose in intra-abdominal infection modeled by CLP mice, either alone, or in combination with standard of care antibiotics." (PMID 30814582, 2019).
infection (continued). "Further, the accumulated capsular strains induce the secretion of pro-inflammatory cytokines through various signaling pathways, such as TLR4 or NLRP3, ultimately leading to irreversible organic damage, just like the lung tissues of K7-challenged mice at 48 h after infection." (PMID 31191500, 2019). "Furthermore, in comparison to oseltamivir, 20 mg/kg LEP or DPEP could dramatically inhibit the protein expression of TLR4, TLR7 and NF-κB p65 on day 3 post-infection (P < 0.01 or P < 0.05)." (PMID 31551774, 2019). "This study revealed that LEP and DPEP could down-regulate the activity of NF-κB p65 by regulating MyD88-dependent signaling pathways of TLR4 and TLR7, thereby exerting their antiviral effects, and the treatment effects might be more significant in the early phase of infection." (PMID 31551774, 2019). "However, the TLR signaling apparatus can become dysfunctional rather than protective against infection, as with more infections seen in cirrhotic patients with TLR4 polymorphisms and with TLR2 and TLR4 dysfunction." (PMID 31627733, 2019). "A slight but statistically significant upregulation of the TLR4 (2.7-fold) and TLR5 (3.4-fold) genes was observed in the spleen of S. Gallinarum-infected chickens compared to both S. Typhimurium-infected animals and uninfected control chickens at 5 days post-infection." (PMID 31998655, 2019). "The expressions of TLR3 and TLR4 were not modified either by the infection or the supplementations." (PMID 31405262, 2019). "Also, the gene expression of TLR4 was evaluated because it is a receptor of innate immunity for LPS and can increase due to infection with gram-negative bacteria." (PMID 31316304, 2019). "Moreover, the absence of signals mediated by MyD88, TLR2, or TLR4 reduced nitric oxide synthase 2 (Nos2) mRNA expression during infection." (PMID 30555476, 2018). "Our results showing that TLR4 and IFNAR1 in the placenta have fetus-protective roles reveal an unexpected outcome of the action of innate receptors that opposes the effects of maternal receptor counterparts and thereby expose a maternal-fetal conflict in the response to infection." (PMID 29440369, 2018). "Shed glycoprotein is sufficient to stimulate cytokine responses in the absence of infection, suggesting that noninfected TLR4-expressing cells stimulated by shed glycoprotein might contribute to the complex inflammatory response in EBOV disease." (PMID 30571771, 2018). "However, it was shown from their data that IL4 was not expressed after infection and TLR4 decreased after infection." (PMID 29433383, 2018). "However, none of the HEU infants investigated in this study had severe infections in the year after their birth suggesting an alternative or compensatory mechanism to TLR4 function in infants non-responsive to LPS stimulation." (PMID 29491865, 2018). "Studies published in14 showed that the E3 protein called “RIDα” attenuated NF-κB activation during an acute infection, and was also sufficient to modulate NF-κB activity downstream of TLR4 signaling independent of infection or expression of other HAdV proteins." (PMID 30090876, 2018). "Interestingly, unlike lethal influenza virus, which failed to cause lethal infection in TLR4−/− mice, EBOV appeared to be equally lethal in wild-type (wt) and TLR4−/− mice." (PMID 28442605, 2017). "Because CO is able to inhibit TLR4 signaling and because KSHV infection activates TLR4 signaling, we next tested whether the expression of IL-1β and IFNβ in KSHV-infected iLEC could be reduced by delivering CO to iLEC immediately prior to infection." (PMID 28421060, 2017). "As expected, the absence of TLR2 or TLR4 did not alter the susceptibility of the macrophage to the infection, suggesting that the cellular signaling through these innate immune receptors, mainly TLR2 and TLR4, is required for IL-27p28 production during T. cruzi infection." (PMID 29033934, 2017).
infection (continued). "In addition, the eggs of worms in the liver of the C. sinensis-infected mice were all detected in the present study (with the 100% infection rates regardless of TLR4mut or TLR4 wild mice)." (PMID 28634394, 2017). "None of the WT or TLR4−/− mice died from the infection during the course of the study." (PMID 28536433, 2017). "The difference in the expression of EGFR during infection and activation of HGEC was a discrepancy that has also been observed in human monocytes, reflecting the fact that live bacteria signaled mostly through TLR-2 and TLR-4, while purified LPS-Pg acted through TLR-2." (PMID 28748038, 2017). "While the binding of LPS to toll-like receptor 4 rapidly activates NF-κB which in turn induces cytokine and chemokine expression, LPS is also known to stimulate the release of TNF-α, an acute phase protein that is rapidly elevated in response to injury or infection." (PMID 26860080, 2016). "However, infection of TLR-4-deficient mice with E. coli also resulted in a strong increase in exfoliation, suggesting that LPS, or more precisely LPS sensing by TLR-4, is not required to trigger exfoliation." (PMID 27171273, 2016). "Maintenance of an optimal level of the surface TLR4 via continuous replenishment of TLR4 from intracellular compartments such as the Golgi apparatus and endosomes is also crucial for macrophage activation upon infection by Gram-negative bacteria." (PMID 27748405, 2016). "In order to analyze the role of TLR2 and TLR4 in the control of B. microti infection, WT B10, TLR2−/−, TLR4−/− and TLR2×4−/− mice were infected ip with a sublethal dose (105 cfu) of B. microti and bacterial load was determined in spleen and liver 3, 7, 14, and 21 days after infection." (PMID 28119856, 2016). "Thus, TLR4 can upregulate the expression of cytokines, such as TNF-α, IFN-γ, IL-6, IL-8, IL-12, and IL-10, thereby increasing resistance to pathogen invasion and infection." (PMID 26576220, 2015). "Even though TLR4 and its ligand LPS have been widely studied, the present simultaneous transcriptional analysis of host and pathogen provide novel insight into the time course of PAMP synthesis and PRR-dependent inflammatory response to A. pleuropneumoniae at the site of infection." (PMID 26018580, 2015). "However, it is known that the TLR4 in the soma of neurons in TGs is not directly involved in pulp inflammation or infection in AP rats." (PMID 26224622, 2015). "Thus, the recognition of LPS via TLR4 is critical for host defense responses against infection by Gram-negative bacteria." (PMID 26639190, 2015). "The blocking of TLR2 or TLR4 did not affect alveolar survival during infection." (PMID 24489729, 2014). "However, we show for the first time that S100A9 alone can directly activate TLR4 (in the absence of LPS) and contribute to the regulation of inflammation during infection with IAV, a non-LPS-expressing pathogen." (PMID 24391503, 2014). "To determine whether defects in the leukocyte response could account for poor control of infection and transmission in the absence of TLR4, we inoculated 100 CFU of B. bronchiseptica into groups of four HeJ or HeN mice." (PMID 24497924, 2014). "In the bladder and in the kidney epithelia, expression of TLR4 is an important surveillance strategy against Gram negative bacteria infections, particularly uropathogenic E. coli, controlling inflammatory responses to such infections." (PMID 25161655, 2014). "The accumulation of CD11b+Ly-6Chigh leukocytes in the brain was slightly, but not significantly, higher in TLR3−/− mice following IC infection of JEV, as compared to wild-type mice, and TLR4−/− mice showed no significant change in leukocyte accumulation by IC infection of JEV." (PMID 25188232, 2014). "However, despite no TLR4 function, infection of hESC-EC with live Haemophilus influenzae induced a concentration-dependent release of CXCL8." (PMID 24690886, 2014).